IL10 (interleukin 10)
Diseases named in the same sentence as IL10 in open-access papers (continued):
Sharing a sentence is not in itself a finding about the gene and the disease.
tumor (continued). "Conversely, M2 macrophages, polarized by IL-4, are associated with tissue repair, anti-inflammatory responses, and tumor promotion, marked by arginase (ARG-1), IL-10, TGF-β, and the mannose receptor (CD206)." (PMID 39795180, 2024). "recently showed that an IL-10-Fc fusion protein led to increased expansion and effector function of terminally exhausted CD8+ TILs, thereby enhancing immune-related anti-tumor response." (PMID 39411143, 2024). "Cytokine profiling from serum samples demonstrated elevated levels of interleukin-10 (IL-10) and transforming growth factor-beta (TGF-β), both of which are indicative of a tumor-promoting immunosuppressive state." (PMID 39795579, 2024). "Specifically, fermented milk inhibited breast cancer cell proliferation, reduced tumor size, and modulated cytokines (downregulated IL-6 levels and upregulated TNF-α, IL-4, and IL-10 levels)." (PMID 39605907, 2024). "The study also revealed that significant cell death can trigger cytokines like IL‐4, IL‐10, IL‐13, and TGF‐β, which aid in efferocytosis‐induced wound healing and further support the progression of metastatic tumours." (PMID 38501838, 2024). "M2-like TAMs are primarily activated by IL-10 and TGF-β, expressing CD163, CD204 and CD206, secrete IL-10, TNF, CCL17, among others, which exerting pro-tumor effects." (PMID 38270700, 2024). "Mechanically, TAMs interact with bone marrow stromal cells(BMSCs) to acquire the function of secreting IL-6 and IL-10, poorly secreting IL-12 and TNF-α, which are suitable for tumor growth." (PMID 38464531, 2024). "M2 macrophages produce anti-inflammatory cytokines such as IL-10 and TGF-β, thereby promoting tumor immune escape." (PMID 38539232, 2024). "Traditionally viewed as an immune suppressant, IL-10 curbs TH1 and cytotoxic T-cell responses, promoting an immunosuppressive microenvironment conducive to tumor evasion." (PMID 39035007, 2024). "Tumor cells attract circulating monocytes to the TME in response to several stimuli such as VEGF, CSF-1, TGF-β, GM-CSF, IL-6, IL-10, and chemokines." (PMID 38935134, 2024). "The authors identified that the combination of sBTLA and an HSP70 vaccine significantly improved the anti-tumor immune response, with combination treatment increasing expression of IL-2, IFN-γ, and CD8+ TILs, and reducing expression of IL-10, TGF-β, and Foxp3." (PMID 38822401, 2024). "The secretome testing on the cell supernatant of the SENP3 deletion group indicated down-regulation of the anti-tumor factors (CCL5 and IL-β) and up-regulation of tumor-promoting factors (IL-10 and TGF-β)." (PMID 39123188, 2024). "Tumour-derived exosomes released by various tumour cells induce the expansion and immunosuppression of MDSCs through exosomal proteins, such as PGE2, TGFβ, Hsp72, IL-10, or IL-16." (PMID 38893071, 2024). "M2 macrophage mainly secrete anti-inflammatory cytokines such as Arginase-I, IL-10 and TGF-beta, which have the function of reducing inflammation and promoting tumor growth and immunosuppression." (PMID 38965594, 2024). "Tumor cells also induce the expression of FasL in endothelial cells via vascular endothelial growth factor-A (VEGF-A), IL-10, and prostaglandin E2 (PGE2), thereby eliciting specific cytotoxic effects in effector T cells." (PMID 38840908, 2024). "They release anti-inflammatory cytokines such as IL-1, IL-10, and TGF-β to create an immunosuppressive environment and suppress the anti-tumor activities of T cells or NK cells." (PMID 38673829, 2024). "By binding to mRNA transcripts containing AU‐rich elements, GAPDH regulates and reduces the production of tumor TNF‐α, while inducing the production of IL‐10 in macrophages stimulated by LPS in a dose‐dependent manner." (PMID 39492834, 2024). "Pro-inflammatory TAMs express TH1 response-inducing cytokines such as IL1α, IL1β, IL12 and TNFα while pro-tumor TAMs express IL10, CCL8, and CCL22 that are tumor promoting." (PMID 38802355, 2024).
tumor (continued). "Significant correlations between the LGALS3 and IL-10 mRNA levels were observed in the LIHC normal and tumor tissues, and also in the normal liver tissues." (PMID 38793619, 2024). "Increases M1 macrophages, enhances the expression of anti-tumor cytokines (IFN-γ, TNF-α, and IL-12), and reduces the level of pro-tumor cytokines (IL-10, IL-4, and TGF-β)." (PMID 38361933, 2024). "TAM-derived IL-10 and TGF-β promote Treg differentiation and expansion, while Treg-mediated CTLA-4 expression and IL-10 release further dampen the anti-tumor immune response." (PMID 39450177, 2024). "On the other hand, the M2 phenotype was often raised as the TAMs mimicked phenotype since it activated immunosuppressors and tumor growth factors such as TGF-β, IL-10, PD-L1, VEGF, and MMPs23,24." (PMID 38589471, 2024). "This immunosuppressive environment is controlled by the tumor through the release of cytokines and other soluble factors such as TNF-α, IL-6, TGF-β, and IL-10, involved in cancer progression." (PMID 39247827, 2024). "Reduced IL-10 levels can lead to the insufficient regulation of TNF-α and anti-tumour T cell responses, fostering tumor-promoting inflammation and contributing to cancer progression." (PMID 39684475, 2024). "M2d has been reported to promote IL-10 and VEGF secretion and to have a pro-angiogenic effect on angiogenesis and tumor progression." (PMID 39203286, 2024). "TRAIL is reported to heighten the production of other pro-tumor inflammatory cytokines, such as IL-10, which inhibits the activity of NK cells and CD8+ T cells within the tumor microenvironment." (PMID 39056714, 2024). "In co-culture with tumor cells and monocytes, stCAR T cells exhibited anti-tumoral activity and potent release of CRS-related cytokines (IL-6, IFN-γ, TNF-α, GM-CSF, IL-2, IL-10)." (PMID 38514793, 2024). "Secondly, Tregs secrete anti-inflammatory cytokines like IL-10 and TGF-β, which dampen the activation and effector functions of tumor-specific CD4+ helper and CD8+ killer T cells [1154]." (PMID 39273409, 2024). "IL-10 can enhance the immune response and promote anti-proliferative and pro-apoptotic pathways by activating the STAT1 pathway in tumor-resident cells CD8+T." (PMID 39591319, 2024). "Within the tumor core, the TAMs_0, TAMs_1, TAMs_2, and TAMs_7 subpopulations predominantly expressed M2-like macrophage markers (e.g., MRC1, IL10, and CD163), indicating an inclination towards the M2 phenotype." (PMID 38938448, 2024). "Some of these molecules are transforming growth factor beta (TGF-B), interleukin-10 (IL-10), interleukin-4 (IL-4) and the onco-immunogenic molecule CD155 overexpressed in tumor microenvironments (TME), which all play multiple immunosuppressive roles." (PMID 39091493, 2024). "For instance, exercise-induced myokines like IL-10 and CCL4 have been shown to directly reduce tumor cell growth and migration in pancreatic cancer patients." (PMID 39346906, 2024). "TAMs secrete large amounts of IL‐10,45, 46 which induces EMT of tumour cells through STAT3 activation and thus promotes metastasis." (PMID 38506082, 2024). "Cytokine imbalances further exacerbate immune suppression, increasing anti-inflammatory cytokines like IL-10 while reducing pro-inflammatory cytokines such as IFN-γ, thereby shifting the immune response in favor of tumor survival." (PMID 39597826, 2024). "Tumor-derived factors such as VEGF, IL-6, and IL-10 recruit MDSCs which in turn produce more VEGF via STAT3 signaling, thereby establishing a positive feedback loop that potentiates tumor angiogenesis." (PMID 38520006, 2024). "Our results indicate that patients with higher tumor burden (defined by BSI) already at baseline displayed lower autologous (spontaneous) and antigen-specific IL-10 secretion." (PMID 38473247, 2024).
tumor (continued). "Regulatory CD4+ T cells are recognized as acting mostly as suppressors of anti-tumor responses, at least partially through secretion of TGF-b and IL-10, and are deemed as major contributors to the mostly immunosuppressive cytokine milieu described for NMSCs." (PMID 38891095, 2024). "NT5E (CD73), CSF ligands, CD274 (PDL1), IL1B, IL6, and IL10 transcripts were primarily found in the peri necrotic zone, whereas NOS2 (iNOS), TGFB2, and NOX1 expression is localized to cellular tumor regions." (PMID 39272914, 2024). "Within the TME, tumor cells generate various suppressive mediators (i.e., PD-L1, TGF-β, IL-10, PGE2) to counteract efficient immune responses." (PMID 39062986, 2024). "This internalization leads to the polarization of macrophages from M1 to M2, resulting in the secretion of pro-tumor factors such as IL-10, TGF-β, and MMPs, which promote an anti-inflammatory TME and foster tumor progression." (PMID 39766882, 2024). "Soluble factors such as cytokines (e.g., IL-10) and chemokines (e.g., CCL5, CCL17) shield tumor cells from chemotherapy-induced cytotoxicity by reducing apoptosis and enhancing survival pathways." (PMID 39682256, 2024). "M2d secretes IL-10, vascular endothelial growth factor (VEGF), a major inflammatory factor in the tumor environment, promoting angiogenesis and contributing to tumor growth." (PMID 39104386, 2024). "TIPBs also secretes the immunosuppressive cytokines IL‐10 and TGF‐β, which results in T cell dysfunction and suppression of anti‐tumor immune responses." (PMID 39509319, 2024). "More recently, mouse models of solid tumors treated with a IL-10/Fc fusion protein showed expansion and increased effector functions of exhausted CD8+ TILs, which resulted in tumor eradication." (PMID 39281678, 2024). "Tregs, characterized by CD4+/CD25+/FoxP3+ expression, can inhibit CD8+ T cell cytotoxicity by secreting immunosuppressive cytokines such as interleukin-10 (IL-10) and transforming growth factor-beta (TGF-β), thereby facilitating tumor immune evasion." (PMID 39769460, 2024). "IL-10 exhibited carcinogenic function by activating the STAT3 pathway and inducing Tregs production and exerted anti-tumor effects by downregulating angiogenic factors." (PMID 38918817, 2024). "Consistent with the enhanced tumor suppression following ST bsAb treatment, the level of proinflammatory cytokines such as IL‐10 and CCL4 that inhibit anti‐tumor immunity was significantly decreased." (PMID 39553435, 2024). "For instance, in melanoma, CAF-secreted cytokines such as IL-10, IL-8, CCL2, and TGFβ stimulate macrophage recruitment and polarisation into the M2 phenotype with tumor-promoting functions." (PMID 38715072, 2024). "Meanwhile, IL-10 prevalence within the TME compromises the functionality of dendritic cells (DCs) and safeguards tumor cells from cytotoxic T lymphocyte (CTL)-mediated cytotoxicity by downregulating TAP1 and TAP2." (PMID 38217016, 2024). "IL-10 signaling moderates the PD-1 expression through IL-10R-STAT3 pathway and sustains anti-tumor immunity by preventing excessive exhaustion." (PMID 38291542, 2024). "The administration of Ox-RtH in the mild-treated groups resulted in significantly higher production of IFNγ and IL10 at the 3rd and 5th week after challenge with B16F10 cells, when compared with the control tumor-bearing group." (PMID 39452870, 2024). "BCG enters tumour cells through phagocytosis to stimulate the production of cellular immune factors such as MCP‐1, MDC, TNF and IL‐10, resulting in the weakening of tumour cell differentiation or stopping the replication cycle." (PMID 38165009, 2024). "It is constitutively expressed on FOXP3+ Tregs, resulting in elevated levels of immunoregulatory cytokines IL-10 and TGF-β, which suppress tumor-specific T-cell responses." (PMID 39877377, 2024).
tumor (continued). "Pegilodecakin is a long-acting, PEGylated version of IL-10 which was found to induce the expression of IFN-γ and granzymes in tumor-infiltrating CD8+ T cells, thereby increasing the number and enhancing the activities of CD8 + T cells." (PMID 38520006, 2024). "The functional assessment of MDSCs through the analysis of PTGS2, S100A8, IL10, TGFB1, and VEGFA expression provides a comprehensive view of their immunomodulatory activities within the tumor microenvironment." (PMID 39916959, 2024). "The production of local cytokines (including IL-4, IL-10, VEGF, and TGF β) promotes tumor growth and progress, and up-regulation of immune checkpoints also suppresses tumor immunity." (PMID 38664743, 2024). "For instance, Tregs and MDSCs can promote TAM polarization towards the M2 phenotype by secreting immunosuppressive factors like IL-10 and TGF-β, thereby supporting tumor growth and immune evasion." (PMID 39290697, 2024). "CSCs release galectin-3, growth differentiation factor 15 (GDF-15), interleukin-10 (IL-10), interleukin-13 (IL-13), prostaglandin E2 (PGE2), and transforming growth factor-beta (TGF-β), which are known to modulate the tumor niche." (PMID 38920716, 2024). "According to research, early tumor cells can secrete CCL2, IL-10, TGF-β, etc. and other molecules to draw monocytes into the epithelium and polarize M2 macrophages into TAMs." (PMID 38602556, 2024). "Conversely, IL-10 can hinder antigen presentation and suppress interferon gamma (IFN-γ), thereby potentially dampening anti-tumor immunity." (PMID 39202777, 2024). "The mRNA expression of Arg-1, IL-10, and CD163 were markly up-regulated in tumor samples compared to paracancer tissue samples." (PMID 38822362, 2024). "In the context of OC, infiltrated neutrophils secrete various cytokines, including IL-2, IL-6, IL-10, TNF-α, and VEGF, promoting cancer progression in the tumor microenvironment." (PMID 38279997, 2024). "The 16-biomarker panels were divided into three categories of inflammatory markers (SAA, CRP, NLR, PLR, and LDH), TH1/TH2 cytokines (IL-2, IL-4, IL-5, IL-6, IL-8, IL-10, IFNγ, TNF, and GM-CSF), and HCC tumor markers (AFP and PIVKA-II)." (PMID 38409200, 2024). "IL-10 and TGF-β secreted by M2 macrophages have dual functions: they promote tumor invasion, angiogenesis, and metastasis while also inhibiting the proportion of NK cells and T cells." (PMID 39221244, 2024). "At the molecular level, M2-TAMs induced by iCCA cells promote tumor growth and invasion through the EMT signaling pathway involving IL-10 and STAT3, suggesting a potential new target for iCCA therapy." (PMID 39290697, 2024). "We first analyzed M2 macrophage markers, such as Arg-1, IL-10, and CD163 in tumor and paracancer tissues." (PMID 38822362, 2024). "Next, possibilities of NFκB-based transcriptional regulation of Il10 and Il12a genes due to NLGP-Dectin-1 transduced signal were explored within nuclei of tumor-conditioned mBMDCs, following nuclear translocations of the NFκB subunits, p65 and p50." (PMID 38649988, 2024). "In the immune escape mechanism, immunosuppressive cells within the TME, such as Tregs, MDSCs, and TAMs, secrete inhibitory factors, such as IL-10 and TGF-β, which weaken the anti-tumor effects of T cells and NK cells." (PMID 39741315, 2024). "These cells release inhibitory cytokines, like IL-10 and TGF-β, that dampen the anti-tumor immune response." (PMID 39335494, 2024). "The co-culture of CAFs and monocytes also contained increased IL-10 levels, and compared to the co-culture with PDAC tumor cells, the macrophages showed a trend toward enhanced expression of PD-L1." (PMID 38594506, 2024). "These cell types, in turn, produce IL-10 and TGF-β to further inhibit the anti-tumor response while supporting angiogenesis and tumorigenesis." (PMID 38550613, 2024). "Accordingly, it was possible for the PA, PR, or PS medium to stimulate the production of IL-10 in macrophages and IFN-γ in CD8+T cells in the tumor site." (PMID 38540186, 2024).
tumor (continued). "Many other studies have shown that Tregs in tumors inhibit anti-tumor immune responses by suppressing the production of inhibitory cytokines (e.g., IL-10, TGF-β, IL-35) and suppressing anti-tumor immune responses." (PMID 38571495, 2024). "Cytokines derived from M2 macrophages, such as IL-10 and TGF-β, are considered major mechanisms for suppressing anti-tumor immune activity." (PMID 38646440, 2024). "In contrast, M2 macrophages secrete a large number of cytokines such as IL-10, VEGF and TGF-β, which promote tumor cell proliferation, epithelial mesenchymal transition (EMT) (D) and angiogenesis." (PMID 38428879, 2024). "It has been found that Lf can inhibit tumor growth through MAPK and AKT signaling pathways, and at the same time MAPK is one of the key factors regulating IL-10." (PMID 39591319, 2024). "This process acts as a vicious cycle, in which M2-type TAM cells are stimulated by the tumor itself, releasing factors like TNF and interleukins such as IL-6, IL-1b, and IL-10, which promote tumor proliferation and survival." (PMID 38248305, 2024). "Some of them, including CCL4, IL10, and THBD, have well-studied mechanisms that contribute to tumor growth promotion." (PMID 38832259, 2024). "Meanwhile, macrophages can promote tumor invasion and metastasis through secretion of various cytokines (e.g., TGF-β, IL-10, arginase 1) and chemokines (e.g., CCL5, CCL17, CCL18, CCL22)." (PMID 38637499, 2024). "This indicates the dual role of IL10 in CAC: on the one hand, it acts to suppress colon inflammation, but on the other hand, it contributes to tumor growth." (PMID 38506672, 2024). "Tregs, in turn, produce IL-10 and TGF-β, which inhibit the immune functions of dendritic cells (DCs) and T cells, thereby preventing the destruction of BCC tumor cells." (PMID 39200233, 2024). "MDSCs are potent producers of the immunosuppressive cytokine IL-10, which plays a key role in mediating MDSC suppression of anti-tumour immunity." (PMID 38464388, 2024). "TAMs also induce immunosuppression through secreting cytokines such as IL-10 and TGF-β to prevent tumor cells from being attacked by natural killer and T cells during progression and after recovery from chemotherapy or anti-tumor immune." (PMID 39108262, 2024). "Using a human M-MDSC model, we show that tumor-derived PGE2 steers moMDSCs towards the acquisition of a suppressive phenotype as seen by the upregulation of CD14, IL-10 and PGE2 production, or the downregulation of HLA-DR." (PMID 38343540, 2024). "In multivariate analysis, age, length of hospital stays, IL-8, IL-10, CD8 cell, and NK cell remain as significant predictors of severity, and age, tumor, IL-8, CD8 cell, and NK cell as significant predictors of mortality." (PMID 38173531, 2024). "Intriguingly, multifactorial analysis of tumor tissues unveiled a significant decrease in the expression of immunosuppressive cytokines, encompassing MCSF, IL-10, and VEGF, within the shCsf1 + RT group." (PMID 39165639, 2024). "These M2-type macrophages can secrete IL-10 and TGF-β to suppress immune T-cells, produce VEGF and bFGF to stimulate tumor angiogenesis, as well as express and secrete a great amount of eHSP90α to create an eHSP90α-rich tumor microenvironment." (PMID 38994997, 2024). "Extensive research has demonstrated that within the HCC tumor microenvironment, hypoxia and factors like PGE2 and TGF-β, secreted by tumor cells, induce Kupffer cells to release interleukin-10 (IL-10), further contributing to immune suppression." (PMID 39679376, 2024). "They produce anti-inflammatory cytokines like IL-10 and TGF-β and secrete factors like VEGF that promote new blood vessel formation (angiogenesis), aiding tumor growth and survival." (PMID 39200315, 2024). "Tumor cells express excessive immunosuppressive molecules, such as PD-L1 and PD-L2, and immunosuppressive factors, such as TGF-β and IL-10." (PMID 39194667, 2024).